MT1X (metallothionein 1X)
Description:
Metallothioneins have a high content of cysteine residues that bind various heavy metals; these proteins are transcriptionally regulated by both heavy metals and glucocorticoids. May be involved in FAM168A anti-apoptotic signaling.
Synonyms: MT-1l; MT1
Tractability: PROTAC: ubiquitination databases record sites on it.
Gene: Protein-coding gene on chromosome 16 (56,682,468 to 56,684,196, forward strand). Ensembl gene ENSG00000187193.
Pathways (Reactome):
Cellular responses to stimuli: Metallothioneins bind metals
Gene Ontology:
Molecular function: protein binding; metal ion binding; zinc ion binding
Biological process: cellular response to cadmium ion; cellular response to erythropoietin; cellular response to zinc ion; cellular response to copper ion; detoxification of copper ion; intracellular zinc ion homeostasis; negative regulation of growth; response to metal ion
Cellular component: cytoplasm; nucleus
Genetic constraint (gnomAD): Loss-of-function variants: 7 observed, 9.66 expected, observed/expected ratio (o/e) 0.72, 90% interval 0.41 to 1.36. That is too few expected variants to judge how well the gene tolerates losing a copy. Missense variants: 72 observed, 78.76 expected, observed/expected ratio (o/e) 0.91, 90% interval 0.75 to 1.11. Synonymous variants: 25 observed, 29.19 expected, observed/expected ratio (o/e) 0.86, 90% interval 0.62 to 1.2.
Homologues: Orthologues: chimpanzee MT1X (100% identical), macaque MT1X (97% identical), rat Mt2A (87% identical), mouse Mt2 (85% identical), guinea pig MT1X (79% identical), zebrafish mt2 (62% identical). Paralogues in human: MT2A (90% identical), MT1H (89% identical), MT1B (87% identical), MT1G (87% identical), MT1A (85% identical), MT1HL1 (85% identical), MT1F (84% identical), MT1M (82% identical), MT3 (69% identical), MT4 (64% identical), MT1E (51% identical).
Diseases named in the same sentence as MT1X in open-access papers:
MT1X is named in the same sentence as 52 diseases in open-access papers, as found by Europe PMC text mining. Sharing a sentence is not in itself a finding about the gene and the disease. The quoted sentences say what the papers report.
breast carcinoma (8 papers, 2007 to 2024). "MT1X was overexpressed in many cancers, including breast cancer, and was a prognostic marker for invasive ductal carcinoma and renal carcinoma." (PMID 38283944, 2023). "Previous studies indicate that downregulation of CXCL14 is associated with prognosis in gastric cancer patients, MT1X may aid in the prognostic discrimination of oral squamous cell carcinoma cases, and MARCO expression is associated with breast cancer survival and risk of recurrence." (PMID 27567667, 2016). "Overall, all genes showed lower expression in four breast cancer cell lines than in the HMEC cell line, except MT1F and MT1X, where MT1F has lower in HMEC than in MCF7 and MDA-MB231 cells, and MT1X has a similar level in MDA-MB231 cells." (PMID 25763113, 2015). "However, the exact functions mechanism of MT-1X in breast cancer remains unknown." (PMID 24690879, 2014). "This suggested that HOXC10, FXYD1, MT1X, and IGF2 may play an important role in the development of luminal A breast cancer under the regulation of HOXC-AS3, AC020907.2, AC026461.1, and AC132217.1." (PMID 35692369, 2022). "By establishing a link between MT-1X and FHL3, our findings suggest that FHL3 may be involved in the regulating the function of MT-1X in breast cancer cell as a MT-1X interactor." (PMID 24690879, 2014).
glioma (4 papers, 2019 to 2024). A benign or malignant brain and spinal cord tumor that arises from glial cells (astrocytes, oligodendrocytes, ependymal cells). "The analysis of MT1A, MT1E, MT1X, MT2, MT3 gene mRNA expression was determined in n = 51, n = 53, n = 49, n = 55, n = 51 glioma patients respectively." (PMID 30932010, 2019). "Here we checked MT1A, MT1E, MT1X, MT2, MT3 gene expression level and epigenetic regulation for one of the highly expressed metallothioneins, MT1A, in different grade gliomas and looked for clinical significance of MT gene activity in glioma tissue in terms of patient survival." (PMID 30932010, 2019).
hepatocellular carcinoma (4 papers, 2014 to 2023). A malignant tumor that arises from hepatocytes. "To elucidate the molecular mechanism by which MT-1X expression regulated hepatoma cells growth, we investigated the effect of MT-1X on the expression of several cell cycle-related proteins by immunoblotting." (PMID 24690879, 2014). "The expression of MT1X in hepatoma cells was found to correlate with the extent of malignancy." (PMID 36639407, 2023). "Given that the role of FHL3 in human hepatoma cell, we sought to determine whether MT-1X could play a role in the regulation of FHL3-mediated human hepatoma cell growth." (PMID 24690879, 2014).
esophageal cancer (3 papers, 2022 to 2024). A primary or metastatic malignant neoplasm involving the esophagus. "Here, we selected the MT1X gene, which has the highest weight in the risk model, and performed corresponding knockdown and suppression experiments in oesophageal cancer cells and normal cells to assess its effect on the development of ESCC." (PMID 37091857, 2023). "MT2A, MT1E, MT1X expression is associated with CD8+ T cell infiltration in malignant tumors including esophageal cancer." (PMID 36466860, 2022). "The expression of MT2A, MT1E and MT1X in esophageal cancer patients and normal controls was detected by TCGA database, and it was found that the expression of MT2A, MT1E and MT1X in esophageal cancer patients was significantly reduced, which was associated with poor prognosis." (PMID 36466860, 2022). "MT1X, a gene involved in the lysosomal pathway, exhibited a lower expression in esophageal cancer cells when compared to normal esophageal epithelial cells." (PMID 38893622, 2024). "The results show that when the MT1X gene was further knocked down in the esophageal cancer cells, the number and proportion of tumour cells in the S and G2+M phases of the cell cycle increased." (PMID 37091857, 2023). "This suggests that the proliferation and growth of esophageal cancer cells were significantly promoted after knocking down the MT1X gene." (PMID 37091857, 2023). "On this basis, we further confirmed the microscopic role of the lysosomal pathway in the invasion and metastasis of esophageal cancer by knocking down the lysosomal pathway gene - MT1X in cellular assays." (PMID 37091857, 2023). "Cellular assays showed that the lysosomal pathway gene MT1X was less expressed in oesophageal cancer cells than in normal oesophageal epithelial cells." (PMID 37091857, 2023). "The expression of MT2A, MT1E and MT1X in esophageal cancer patients and normal persons was detected by TCGA database, and it was found that the expression of MT2A, MT1E and MT1X in esophageal cancer patients was significantly reduced." (PMID 36466860, 2022). "The expression of MT2A, MT1E and MT1X in esophageal carcinoma and their relationship with CD8+ T cell infiltration were detected." (PMID 36466860, 2022). "Knocking down MT1X significantly enhanced the growth rate of esophageal cancer cells." (PMID 38893622, 2024). "Knockdown of MT1X significantly promoted the growth rate of oesophageal cancer cells." (PMID 37091857, 2023). "TCGA database was used to analyze the relationship between expression of MTA2, MT1E and MT1X in esophageal cancer and prognosis and survival, and the analysis results showed that low expression of MT2A, MT1E and MT1X was associated with poorer overall survival." (PMID 36466860, 2022). "GEPIA database analysis, MT1E, MT1X molecule transcription levels in esophageal cancer patients and normal control group MT2A, MT1E, MT1X molecule." (PMID 36466860, 2022).
gastric cancer (3 papers, 2015 to 2019). A primary or metastatic malignant neoplasm involving the stomach. "Methylation inactivation in tumor suppressors genes, such as MT1M, MT1H, MT1X, and HRK, is responsible for the development of various cancers, such as prostate cancer, liver cancer, colorectal cancer, and gastric cancer, but loss of these genes may be linked with the pathogenesis of BRCA." (PMID 31311202, 2019). "We performed Quantitative Real-time PCR (qPCR) on 6 up-regulated genes (COL1A, BGN, SPP1, MELK, IGFBP4, SPARC) and 4 down-regulated genes (PGC, SST, MT1X, S100P) to verify our data in gastric cancer tissues (Tumor) and noncancerous tissues (Normal)." (PMID 25928635, 2015).
sarcopenia (3 papers, 2022 to 2024). Progressive decline in muscle mass due to aging which results in decreased functional capacity of muscles. "In this research, six genetic biomarkers closely associated with sarcopenia, including ARHGAP36, FAM171A1, GPCPD1, MT1X, ZNF415, and RXRG, were identified by WGNCA and LASSO analysis, which were used to future diagnose and screen for sarcopenia." (PMID 36147639, 2022). "Additionally, in patients with sarcopenia, MT1X and ARHGAP36 were upregulated, whereas FAM171A1, GPCPD1, ZNF415 and RXRG, were downregulated, demonstrating high diagnostic accuracy for sarcopenia and potential as predictive markers for screening." (PMID 38337720, 2024). "Finally, six hub genes with AUC exceeding 0.9, including GPCPD1, MT1X, ARHGAP36, FAM171A1, ZNF415, and RXRG, were defined as diagnostic biomarkers of sarcopenia." (PMID 36147639, 2022). "Moreover, six hub genes with AUC exceeding 0.9, including ARHGAP36, FAM171A1, GPCPD1, MT1X, ZNF415, and RXRG, were confirmed as diagnostic biomarkers for sarcopenia." (PMID 36147639, 2022). "We found the AUC values of GPCPD1, MT1X, ARHGAP36, FAM171A1, ZNF415, and RXRG on the validation dataset were 0.928, 0.75, 0.978, 0.961, 0.811, and 0.906, indicating that the six biomarkers had high diagnostic accuracy for sarcopenia." (PMID 36147639, 2022). "Compared to normal samples, the expression levels of both MT1X and ARHGAP36 were upregulated in sarcopenia samples, while GPCPD1, FAM171A1, ZNF415, and RXRG showed lower expression in sarcopenia samples." (PMID 36147639, 2022).
atherosclerosis (2 papers, 2016 to 2025). A disease characterized by the build-up of fatty material and calcium deposition in the arterial wall resulting in partial or complete occlusion of the arterial lumen. "In fact, fetal high-density lipoprotein, which is associated with the inhibition of atherosclerosis, reduces the expression of MT-1X and MT-2A in human placental endothelial cells." (PMID 27563876, 2016). "This reveals that PPARG and MT1X may be beneficial genes for atherosclerosis." (PMID 40824771, 2025). "The KGs of T cells involved in the effects of hawthorn on the PVAT microenvironment in atherosclerosis were CCL3, CCL4, MT2A, and MT1X." (PMID 40824771, 2025).
bladder cancer (2 papers, 2017 to 2022). "Further analysis of the 3 independent bladder cancer datasets have identified ACOX1, UPK2, TRAK1, PLEKHG6 and MT1X genes had their expression significantly correlated with that of DAPK1." (PMID 28388658, 2017).
neuroblastoma (2 papers, 2021 to 2024). Neuroblastoma (NB) is the most common solid, extracranial childhood tumor. "In a previous report of our laboratory, phenotyping of MYCN-amplified Kelly and SK-N-BE-2-C neuroblastoma cell lines, a high expression variance of metallothionein genes, such as MT2A and MT1X, was already reported, especially in Kelly cells." (PMID 34066513, 2021).
Obesity (2 papers, 2021 to 2024). Accumulation of substantial excess body fat. "However, noteworthy, evidence has shown downregulation of MT1X and MT1G expression in lymphoblastoid cells of male subjects with non-syndromic obesity in comparison to lean subjects." (PMID 33652748, 2021).
oral squamous cell carcinoma (2 papers, 2012 to 2016). "We next determined MT1X protein expression levels in primary oral squamous cell carcinoma and knocked down its expression in Tca/PYM cell by siRNA." (PMID 23251525, 2012).
periodontal disease (2 papers, 2019 to 2022). "The present validation study confirmed that the genes for the MT1F, MT1X, MT1M, MT1E, and MT2A isoforms exhibit a statistically significant alteration of expression in Down’s syndrome patients with active periodontal disease and implant failure." (PMID 35741790, 2022).
prostate carcinoma (2 papers, 2019 to 2022). A carcinoma that arises from epithelial cells of the prostate gland. "In gastric and prostate cancers, overexpression of DNA damage inducible transcript 4 (DDIT4) and the metallothionein MT1X have both been identified to associate with poorer prognosis and/or increased metastatic phenotypes." (PMID 35614362, 2022).
psychosis (2 papers, 2008 to 2023). "Using a quantitative PCR, we validated a set of genes such as up-regulated metallothioneins (MT1E, MT1F, MT1H, MT1K, MT1X, MT2A and MT3) and down-regulated neuropeptides (SST, TAC1 and NPY) in the dorsolateral prefrontal cortex of psychosis patients." (PMID 18992145, 2008). "In the current cross-study analysis, we identified a set of metallothionein genes including MT1X, MT1K, MT1E, MT1H, MT1F, MT2A and MT3 that are significantly up-regulated in psychosis." (PMID 18992145, 2008). "In a study conducted on postmortem subjects with and without psychosis, up-regulation in MT1E, MT1F, MT1H, MT1K, MT1X, MT2A, and MT3 genes was observed in the dorsolateral prefrontal cortex." (PMID 36831126, 2023).
astrocytomas (1 paper, 2019). "MT1A, MT1E, MT1X, MT2, MT3 gene expression was elevated in grade IV astrocytomas (glioblastomas) as compared to astrocytomas grade I-III." (PMID 30932010, 2019). "Analysis showed the trend for increasing MT1A, MT1E, MT1X, MT2 and MT3 gene expression in higher malignancy tumours, e.g. glioblastomas as compared to I-III grade astrocytomas." (PMID 30932010, 2019).
Cachexia (1 paper, 2022). Severe weight loss, wasting of muscle, loss of appetite, and general debility related to a chronic disease. "In addition, consistent with higher percentage of effector-memory CD8+ T cells in non-cachexia patients, genes relevant to the dysfunctional phenotype and the state of inactivation such as MT1X, MT1E, IL7R, and ZFP36L2 were highly expressed in CD8+ T cells in non-cachexia patients." (PMID 36376273, 2022).
Cirrhosis (1 paper, 2021). A chronic disorder of the liver in which liver tissue becomes scarred and is partially replaced by regenerative nodules and fibrotic tissue resulting in loss of liver function. "MT1X was upregulated in the human hepatoma cell line HepG2 with acute exposure to cadmium chloride, whose major toxicological effects were liver hyperplasia, liver tumor, liver degeneration, fibrosis, and cirrhosis." (PMID 34676244, 2021).
clear cell renal cell carcinoma (1 paper, 2024). "The greater the MT1X expression in patients with clear cell renal cell carcinoma, the greater the likelihood of both highly graded tumors and metastasizing tumors." (PMID 39061894, 2024). "Therefore, MT1X can predict tumorigenesis to some extent and predict the prognosis of clear cell renal cell carcinoma." (PMID 39061894, 2024).
COVID-19 (1 paper, 2023). A disease caused by infection with severe acute respiratory syndrome coronavirus 2. "In our data, the response to cytokine pathway also shows upregulated expression of MT2A and MT1X in the COVID-19 patients." (PMID 37886355, 2023). "Interestingly, we found metal ion homeostasis pathway associated with metallothionein (MT2A, MT1E, and MT1X) genes enriched within CD8+ TCM, CD8+ TEM, and activated CD4+ T cells in the COVID-19 positive individuals." (PMID 37886355, 2023).
esophageal adenocarcinoma (1 paper, 2021). A malignant tumor with glandular differentiation arising predominantly from Barrett mucosa in the lower third of the esophagus. "Transcriptomics showed that the combination of SLC26A9 and the other four genes, SINHCAF, MICB, KRT19, and MT1X, became a gene signature that predicts the overall survival of esophageal adenocarcinoma." (PMID 35008199, 2021).
esophageal squamous cell carcinoma (1 paper, 2022). Esophageal squamous cell carcinoma (ESCC) is a type of esophageal carcinoma (EC) that can affect any part of the esophagus, but is usually located in the upper or middle third. "Therefore, MT2A, MT1E, MT1X may be potential predictors of anti-PD-1 therapy in patients with advanced esophageal squamous cell carcinoma." (PMID 36466860, 2022).
follicular carcinoma (1 paper, 2017). "In fact, TSHR stimulation induced expression of metallothionein isoform 1X (MT1X) in human follicular carcinoma cells." (PMID 28923001, 2017).
metastatic disease (1 paper, 2022). "Further, MT1X expression levels were higher in patients with higher tumor grades and metastatic disease." (PMID 36149322, 2022).
ovarian carcinoma (1 paper, 2025). A malignant neoplasm originating from the surface ovarian epithelium. "CAOV3 HGSC cells were selected, due to uniquely restricted expression among all ovarian cancer cell lines of only MT2A and MT1X, with MT2A as the predominantly expressed metallothionein." (PMID 39858588, 2025).
thyroid cancer (1 paper, 2024). "In thyroid cancer, compared to malignant cells of the primary tumor, the characteristic of lymph node metastatic cells is the upregulation of MT1X and MT1G." (PMID 38747739, 2024).
viral infection (1 paper, 2020). "The top-scoring genes in the network include the members of Interferon Induced Transmembrane Proteins (IFITM1 and IFITM3) followed by MT1E, MT1X, and MT1G and OASL, all essential proteins involved in the innate immune response to viral infection." (PMID 32012164, 2020).